OAS1 (2'-5'-oligoadenylate synthetase 1)
Diseases named in the same sentence as OAS1 in open-access papers (continued):
Sharing a sentence is not in itself a finding about the gene and the disease.
breast carcinoma (continued). "High mRNA expression of OAS1 and OAS3 were correlated with worse prognosis for all breast cancer patients, whereas OAS2 was associated with favorable prognosis." (PMID 32560641, 2020). "In luminal B type breast cancer, high mRNA expression of OAS1 was correlated with worse OS (HR = 1.61, 95%CI: 1.02–2.54, p = 0.04)." (PMID 32560641, 2020). "It is interesting that Zhang Wang’s report shows that OAS1 was associated with the poor prognosis of breast cancer, we did not observe this result in this study." (PMID 37746262, 2023). "Moreover, a recent study revealed that high expression of OAS1 predicts poor survival in breast cancer patients." (PMID 35810383, 2022). "However, high expression of OAS1 and OAS3 was significantly associated with worse overall survival in Luminal A breast cancer." (PMID 36430510, 2022). "Moreover, our study further demonstrated that high OAS1 expression predicts poor survival in breast cancer patients, especially in subgroups with LN-negative, luminal A, luminal B, grade I and grade II tumors." (PMID 32560641, 2020). "OAS1, OAS2, and OAS3 were significantly associated with prognosis for all breast cancer patients." (PMID 32560641, 2020). "High mRNA expression of OAS1 (HR = 2.01, 95%CI: 1.26–3.18, p = 0.0026), OAS3 (HR = 1.72, 95%CI: 1.13–2.64, p = 0.011) and OASL (HR = 1.8, 95%CI: 1.17–2.77, p = 0.0066) was significantly associated with worse OS in grade 2 breast cancer." (PMID 32560641, 2020). "High mRNA expression of OAS1 (HR = 1.5, 95%CI: 1.06–2.14, p = 0.022) and OAS3 (HR = 1.7, 95%CI: 1.19–2.42, p = 0.0029) was significantly associated with worse OS in luminal A type breast cancer patients." (PMID 32560641, 2020). "However, whether OAS1 partially inhibits the growth as well as promotes apoptosis of breast cancer cells through OAS/RNase L pathway remains to be supplemented by subsequent experiments." (PMID 33649294, 2021). "In addition, we used rescue experiments to explore whether OAS1 is involved in the carcinogenic effect of TINCR in breast cancer." (PMID 33649294, 2021). "The constructed predictive model showed that OAS1, OAS2, OAS3, and OASL genes can effectively predict the overall survival of breast cancer patients." (PMID 39633486, 2024). "The experimental data revealed significantly elevated mRNA levels of OAS1, OAS2, OAS3, and OASL in breast cancer cell lines relative to normal controls (p-value < 0.05)." (PMID 39633486, 2024). "Overall, these results highlight the critical roles of OAS1, OAS2, OAS3, and OASL in supporting the growth and proliferation of breast cancer cells, while also suggesting their involvement in modulating cellular migration." (PMID 39633486, 2024). "Next, we validated the promoter methylation levels of OAS1, OAS2, OAS3, and OASL genes in both breast cancer and control samples utilizing the OncoDB database." (PMID 39633486, 2024). "Utilizing the TISIDB database, we explored the relationship between OAS1, OAS2, OAS3, and OASL expression in breast cancer across various immune and molecular subtypes." (PMID 39633486, 2024). "Results from UALCAN and GEPIA indicated that the mRNA levels of OAS1, OAS2, OAS3, and OASL were markedly higher (p-value < 0.05) in breast cancer samples compared to normal samples, aligning with the outcomes observed in cell lines." (PMID 39633486, 2024). "In breast cancer, for instance, there is a notable upregulation of OAS genes such as OAS1, OAS2, OAS3, and OASL." (PMID 39633486, 2024). "The knockdown of OAS1, OAS2, OAS3, and OASL in HOC1 cells, validated by qRT-PCR and Western blot analyses, revealed their critical roles in breast cancer." (PMID 39633486, 2024). "The OAS family genes (OAS1, OAS2, OAS3, and OASL) were found to be significantly upregulated in breast cancer cell lines and tissues compared to normal controls." (PMID 39633486, 2024).
breast carcinoma (continued). "A total of five drugs, Acetaminophen, Estradiol, Cyclosporine, Calcitriol, and Seocalcitol, demonstrated the capability to potentially reduce the expression levels of OAS1, OAS2, OAS3, and OASL, suggesting their prospective use in breast cancer treatment." (PMID 39633486, 2024). "Our study observed significant correlations between the expression of OAS1, OAS2, OAS3, and OASL and various molecular and immune subtypes of breast cancer." (PMID 39633486, 2024). "The results uncovered a significant correlation between the expression of OAS1, OAS2, OAS3, and OASL and all immune molecule subtypes in breast cancer." (PMID 39633486, 2024). "To investigate the correlation between the expression levels of OAS1, OAS2, OAS3, and OASL genes and the survival outcomes in breast cancer patients, we utilized the Kaplan-Meier Plotter online bioinformatics tool." (PMID 39633486, 2024). "To establish interferon induction in breast cancer MDA-MB-231 cultured cells, we looked for interferon stimulated genes (ISG) including: OAS1, OAS3, RIG1, TLR3 and IFI16 genes." (PMID 32817625, 2020). "In summary, we found that high mRNA expression of OAS1 and OAS3 was correlated with worse prognosis in all breast cancer patients." (PMID 32560641, 2020). "Of particular interest for our studies, the activation of ER and progesterone receptor (PR) has been shown to inhibit OAS1 and type I IFN signaling, respectively, in breast cancer models." (PMID 31100952, 2019). "The findings indicated that OAS1, OAS3, and OASL genes did not exhibit mutations among the 986 analyzed breast cancer samples." (PMID 39633486, 2024). "Furthermore, the findings from GEPIA revealed that the expressions of OAS1, OAS2, OAS3, and OASL genes were notably more pronounced in the advanced stages of breast cancer compared to the early stages." (PMID 39633486, 2024). "The comprehensive examination of the mutational landscape of OAS1, OAS2, OAS3, and OASL genes in breast cancer patients revealed that OAS1, OAS3, and OASL exhibited an absence of mutations in all 986 analyzed breast cancer samples." (PMID 39633486, 2024). "Differentially expressed genes, especially those in five modules, including OAS1, IFI27, LPAR1, PTGFR, ITGB4, and ITGA6, might participate in the epithelial-mesenchymal transition process in breast cancer cell line DKTA." (PMID 36289533, 2022). "In order to investigate whether OAS1 mRNA is degraded by SMD, we used qRT-PCR to detect the effect of knocking down STAU1 on the expression of OAS1 in breast cancer cells." (PMID 33649294, 2021). "We have verified that TINCR can regulate OAS1 in breast cancer, while the mechanism was still not clear." (PMID 33649294, 2021). "Given that OAS1–3 and OASL both belong to the OAS family, it is noteworthy to systematically explore whether OAS family members could be prognostic indicators in breast cancer." (PMID 32560641, 2020). "Initially, we evaluated the expression of IFN-signaling proteins (STAT1 (Y701), STAT1, STAT2, IRF9) and IFN-stimulated proteins that induce an antiviral state (OAS1 and MxA) in MCF7/pS, MCF7/pR, 231/pS and 231/pR breast cancer cells in the absence or presence of palbociclib." (PMID 31100952, 2019). "Additionally, results from HPA demonstrated a significant elevation in protein expression levels of OAS1, OAS2, OAS3, and OASL in breast cancer tissue samples as opposed to normal tissue samples." (PMID 39633486, 2024). "Furthermore, our findings indicate a noteworthy negative correlation between OAS1, OAS2, OAS3, and OASL elevated gene expression and a substantial decrease in promoter methylation levels across breast cancer tissues." (PMID 39633486, 2024).
Alzheimer disease (12 papers, 2019 to 2025). A progressive, neurodegenerative disease characterized by loss of function and death of nerve cells in several areas of the brain leading to loss of cognitive function such as memory and language. "As a candidate pathway for detailed characterisation, we selected type I interferon signalling; including OAS1 as a readout which has been identified as an Alzheimer’s disease risk gene." (PMID 40542358, 2025). "Previous studies of transcriptomic and gene association studies have highlighted the potential of the 2′–5′ oligoadenylate synthetase 1 (OAS1) to play a role in Alzheimer’s disease." (PMID 39859237, 2025). "Genome-wide association studies of late-onset Alzheimer’s disease risk predicted OAS1, LAPTM5, ITGAM/CD11b and LILRB4 as four new risk genes for this neurodegenerative disease." (PMID 34943215, 2021). "This study aims to strengthen the evidence that OAS1 can act as a key modulator of the Aβ response and, therefore, a potential avenue to explore in relation to Alzheimer’s disease." (PMID 39859237, 2025). "This study aimed to provide further support and additional evidence for the role of the OAS1 gene in Alzheimer’s disease." (PMID 39859237, 2025). "The variant rs601338 in FUT2 has been associated with resistance to Norwalk virus infection, rs10774671 in OAS1 with diabetes type 1 susceptibility, rs3892097 in CYP2D6 with poor metabolism of debrisoquine, and rs3832852 in A2M with the pathogenesis of Alzheimer's disease." (PMID 39368455, 2024). "The exploration of gene expression analysis using DESeq2 described elsewhere found no significant differential expression of OAS1 between controls and Alzheimer’s disease in the post-mortem frontal cortex tissue." (PMID 39859237, 2025). "These four genes, OAS1, LAPTM5, ITGAM/CD11b and LILRB4, have not been previously reported as having variants significantly associated with Alzheimer’s disease using traditional GWAS approaches." (PMID 32274467, 2019).
influenza (12 papers, 2011 to 2024). An acute viral infection of the respiratory tract, occurring in isolated cases, in epidemics, or in pandemics; it is caused by serologically different strains of viruses (influenzaviruses) designated A, B, and C, has a 3-day incubation period, and usually lasts for 3 to 10 days. "We next assessed expression levels of various cytokines and chemokines (i.e., IFNB1, IFNL1, IFNL2/3, IFIT1, IFIT3, OAS1, MX1, IL‐6, CXCL10, and IFITM1) which were triggered by influenza and OC43 virus infections alone or together by qPCR." (PMID 38556468, 2024). "For instance, hsa-miR-6890-5p, CEBPB, Cyclosporine, Influenza, and RBM39 have interactive relationships centered around OAS1." (PMID 38601162, 2024). "In contrast, several genes involved in the interferon-stimulated innate immune response (OAS1, OAS2, SOCS1, DDX58, 16 CXCL10) were upregulated following influenza superinfection during SARS-CoV-2 infection." (PMID 38178911, 2023). "They found that interferon-related genes such as RSAD2, LAMP3, IFI44L, and OAS1 were significantly differentially expressed in individuals with symptomatic RSV, influenza, or HRV infection." (PMID 24265599, 2013). "Their influenza classifier genes showed mostly IFN regulated genes, several of which (Ifi44, G1p2, Oas1, Zbp1) showed overlap with our signature." (PMID 21731757, 2011).
lupus (12 papers, 2015 to 2025). "Meanwhile, the expression levels of IFN-I signature genes (ISGs), such as Mx1, Irf7, Oas1, and Isg15, were increased in the renal tissues of KI lupus mice compared with WT lupus mice." (PMID 35788118, 2022). "There is a marked difference in the expression of OAS1 between patients with systemic lupus erythematosus (SLE) and healthy individuals, and it has been identified as a biomarker marker for SLE." (PMID 37928544, 2023). "Upregulated H3K4me3 peaks have been identified in immune response genes in systemic lupus erythematosus (SLE), which correlates with increased expression of immune-related genes such as OAS1 and IFI44L." (PMID 40005847, 2025). "The RhoA/ROCK inhibitor in turn reduced type I IFN-induced STAT-1 phosphorylation and ISRE reporter gene expression, as well as OAS1 and CXCL10 in human lupus PBMCs." (PMID 37790522, 2023). "This revealed that three prioritised lupus genes (USP18, STAT1, IFNA1-17) were shared with the 13 category I genes (IFNAR1/2 signal transduction proteins) and four prioritised genes (IRF1/5/8 and OAS1) were shared with the 38 category II genes (transcriptional targets of interferon response)." (PMID 41038828, 2025). "In the present report, RhoA mRNA expression further is shown to be higher in the PBMCs of lupus patients when compared to healthy controls, and expression levels correlate positively with type I IFN scores and interferon-induced genes, including CXCL10, OAS1, IFIT3, and MX1." (PMID 38243295, 2024). "In our project,RhoA mRNA expression further has been shown to be higher in the PBMCs of lupus patients when compared to healthy controls, and expression levels correlate positively with type I IFN scores and interferon-induced genes, including CXCL10, OAS1, IFIT3 and MX1." (PMID 37790522, 2023). "OAS proteins, particularly OAS1, and the editing enzymes ADAR and APOBEC were found upregulated in Systemic Lupus Erythematosus (SLE)." (PMID 35757716, 2022).
ZIKV infection (12 papers, 2017 to 2025). "The Zika virus infection activated the interferon pathway early, as it was evidenced by the detection of interferon-β mRNA and their inducible genes (OAS-1, viperin)." (PMID 36557673, 2022). "Similar to data obtained from RNA-sequencing, qRT-PCR validated that ZIKV infection induces up-regulation of interferon gamma induced protein 10 (IP-10), interleukin-6 (IL-6), 2'-5'-oligoadenylate synthetase 1 (OAS1) and interferon-β (IFN-β) genes." (PMID 32902370, 2020). "RNA-seq analysis of HT-29 cells revealed that ZIKV infection caused the upregulation of IFNB and several innate immune response genes, including FAM60A, IFI6, DDX58, OAS1, MX1, and IP-10." (PMID 30333476, 2018). "At 36 h post-ZIKV infection, the expression levels of interferon-induced antiviral proteins, including ISG15, ISG56, OAS1, OAS2, and OAS3, were increased by TRIM38 overexpression and decreased by TRIM38 knockout." (PMID 40006954, 2025). "In contrast to Zika virus infection, exogenous IFNɛ strongly induced ISG15, OAS1, IFIT1, and IFI6 within 12 hours post-treatment." (PMID 39621805, 2024). "Generation of innate AVPs, including OAS1, OAS2, OASL, and MX1, in response to IL27 was found to be protective against Zika virus infection in human keratinocytes." (PMID 37310504, 2023). "We also found that ZIKV infection induced the expression of OAS2, as well as OAS1 and OAS3 in A549 cells." (PMID 32276512, 2020). "ZIKV infection was shown to induce the expression of the ISGs IFIT1-3, RSAD2/Viperin, and OAS1 in primary human DCs." (PMID 31652496, 2019). "Likewise, ZIKV infection of Vero cells showed a striking reduction in ISG15 and OAS1 gene expression triggered by exogenous addition of IFN." (PMID 31652496, 2019).
type 1 diabetes (11 papers, 2009 to 2024). "The heterozygote SNP (rs10774671) is known to cause loss of function in the OAS1 gene and is a high impact risk factor for susceptibility to Type 1 Diabetes." (PMID 31604968, 2019). "Thus the association with the two OAS1 SNPs, rs10774671 and rs1131454 (former rs3741981), and type 1 diabetes or multiple sclerosis remain elusive." (PMID 25205466, 2014). "A gene encoding 2',5' oligoadenylate synthetase 1 (OAS1) is stimulated by interferon, plays an important role in innate immunity and was previously shown to be genetically associated with Type I Diabetes, multiple sclerosis, SARS and hepatitis C persistent infection." (PMID 19161620, 2009). "Furthermore, this could also explain the association of the SNP rs10774671 G allele, i.e., the OAS1 p46 variant, with multiple sclerosis (MS) and type 1 diabetes, as the mitochondrial dysfunction would drive both of these pathologies." (PMID 31817188, 2019). "GSEA_KEGG analysis suggested that OAS1 was involved in type I diabetes, proteasome, cytokine receptor interaction, NK cell-mediated cytotoxicity, graft-versus-host disease, NOD like receptor signaling pathways, processing and presentation of antigen." (PMID 37746262, 2023). "Genetic variation in OAS1 has been previously associated with other diseases, including Type I Diabetes, SARS, and Hepatitis C. The associations in Type I Diabetes and SARS have been inconsistent in different studies." (PMID 19247438, 2009). "OAS1 may participate in the development of autoimmune diseases, such as type 1 diabetes and systemic lupus erythematosus." (PMID 37746262, 2023). "Moreover, there is a significant increase in the expression of OAS1 in patients with type 1 diabetes, suggesting that the innate immune antiviral system may play a crucial role in the development and progression of type 1 diabetes." (PMID 37928544, 2023). "These include OAS1, C4A, and IFIH1 for Type 1 diabetes and ID3 and C4 for Sjögren’s syndrome." (PMID 30002654, 2018).
autoimmune disease (10 papers, 2010 to 2024). A disorder resulting from loss of function or tissue destruction of an organ or multiple organs, arising from humoral or cellular immune responses of the individual to their own tissue constituents. "Gain-of-function variants of OAS1 can induce dysfunction and apoptosis of macrophages in autoimmune disease patients." (PMID 37928544, 2023). "The expression levels of STAT1 and OAS1 manifest the opposite expression tendency across cancer and autoimmune disease." (PMID 36765396, 2023). "Among ISGs, both ddx58 with IFIT1 and ISG15 with OAS1 showed significant positive correlations in all types of autoimmune disease and HC samples." (PMID 34848794, 2021). "Previous studies on OAS1 have primarily focused on its role in antiviral and anti-infection mechanisms, highlighting its involvement in the immune system and its correlation with various autoimmune diseases." (PMID 37928544, 2023). "Moreover, OAS1 has been reported to play a significant role in the development of numerous autoimmune diseases." (PMID 37928544, 2023). "Our results establish OAS1 as a risk locus for SS and support a potential role for defective viral clearance due to altered IFN response as a genetic pathophysiological basis of this complex autoimmune disease." (PMID 28640813, 2017). "Additionally, other genes that were identified in our study, including BCL2, OAS1, MX1, and SKP2 have been previously associated with various autoimmune diseases." (PMID 29387060, 2017). "From the combined databases in this study, the mRNA levels of STAT1 and OAS1 were increased in IDC while reduced in SLE manifesting the opposite expression tendency across cancer and autoimmune disease." (PMID 36765396, 2023). "Investigations into the commonalities between autoimmune diseases and cancer have highlighted the crucial role of the IFN-JAK-STAT signal related to STAT1 and OAS1, implying that OAS1 may play a significant role in immune homeostasis in both of these diseases." (PMID 37928544, 2023). "The downstream differences of various isoforms in protein levels, isoform expression, responsiveness to IFN, and basal activity between genotypes flag OAS1 as a highly relevant protein in autoimmune diseases, despite no direct effect on IFN expression." (PMID 28640813, 2017). "Additionally, in agreement with a local immune suppression environment, IFIT1, OAS1 and OAS2 are up-regulated in the autoimmune disease systemic lupus." (PMID 20707927, 2010).